INS (insulin)
Diseases named in the same sentence as INS in open-access papers (continued):
Sharing a sentence is not in itself a finding about the gene and the disease.
diabetes (continued). "Insulin resistance, defined as the diminished responsiveness of insulin-target tissues to insulin, is the central pathogenic mechanism underlying obesity-associated disorders such as type 2 diabetes mellitus (T2DM), non-alcoholic fatty liver disease (NAFLD), and atherosclerosis." (PMID 41157128, 2025). "Likewise, dietary habits and physical activity levels were unaccounted for, which is pertinent, as habitual daily activity is associated with insulin sensitivity in pre-diabetes." (PMID 38542217, 2024). "Diabetes is a lifestyle disease caused by impaired glucose metabolism and insulin secretion." (PMID 38945951, 2024). "In addition, Bacteroides enterotypes are an independent risk factor for type 2 diabetes mellitus, attributed to increased LPS levels, causing decreased insulin sensitivity." (PMID 39409832, 2024). "Because adiposity associates with diabetes, we performed insulin and glucose tolerance tests." (PMID 39331703, 2024). "In addition, both high levels of plasma glucose and excessive utilization of free fatty acids by MT due to insulin deficiency or insulin ineffectiveness in diabetes have been reported to generate oxidative stress." (PMID 39057635, 2024). "We cannot overcome diabetes until we understand why this difference occurs between mammals and the lower animals and which organs in diabetes are impaired by insufficient or excessive insulin action, causing complications and diabetes-associated diseases, which we have been trying to explore." (PMID 39513056, 2024). "Certainly, in a case of diabesity, the use of a short-acting glucagon infusion only will aggravate hyperglycaemia; thus, a proper additional insulin therapy would be crucial to maintain euglycaemia and accelerate energy expenditure in patients with insulin-deficient diabetes." (PMID 38579770, 2024). "Additionally, the destruction of pancreatic β-cells, which produce, store, and release insulin, increases the risk of diabetes development." (PMID 39598390, 2024). "Patient-related causes of PIR encompass insufficient knowledge about insulin, lifestyle inconveniences, fear of adverse reactions such as hypoglycemia, anxiety and fear associated with injections, inadequate self-efficacy in diabetes management, and limited social support." (PMID 38803476, 2024). "It remains unclear what levels of 25(OH)D are necessary to influence glucose and insulin homeostasis, and therefore the risk of incident diabetes." (PMID 38459212, 2024). "The persistence of this aberrant hypermethylated state into adulthood can result in insufficient insulin secretion by offspring mice due to the inhibition of gene expression, thereby contributing to the intergenerational inheritance of susceptibility to diabetes mellitus." (PMID 40302954, 2024). "It is well known that the main pathogenic mechanism of diabetes mellitus includes functional defects in islet beta cells, which can lead to insufficient insulin secretion or poor interaction with insulin receptor substrates, resulting in glucose metabolism disorders and eventually hyperglycemia." (PMID 37962815, 2024). "Telemonitoring interventions may have the potential to postpone the start time for insulin treatment and reduce the risk of diabetes-related complications in people with T2D if they focus on diabetes self-management education components." (PMID 38778345, 2024). "Certain β-blockers, particularly nonselective β-blockers, may be associated with adverse effects on glucose metabolism and insulin sensitivity, potentially leading to an increased risk of developing or exacerbating diabetes." (PMID 39759452, 2024). "Studies have shown that interventions such as maintaining a healthy diet, engaging in regular physical activity, and managing body weight are crucial in mitigating the age-related decline in insulin sensitivity and reducing the risk of diabetes and cardiovascular complications." (PMID 39125938, 2024).
diabetes (continued). "Some diabetes medications, such as certain types of insulin and sulfonylureas, may be associated with weight gain, which can exacerbate other risk factors for diabetes-related complications." (PMID 39583077, 2024). "Both population individuals and patients with diabetes manifestations carrying mutations in the HNF4A gene also secrete reduced amounts of insulin in response to glucose and arginine challenge, and have impaired glucagon secretion in response to arginine challenge." (PMID 39902162, 2024). "Few studies have examined the role of cathelicidin in the pathogenesis of T2DM, although LL-37 may help to control blood sugar levels, support the health of insulin-producing cells, and address COVID-19 complications linked to diabetes and hyperglycemia." (PMID 39728453, 2024). "On the other hand, as of the date of writing this report, researchers have not found any previous descriptions of functional hypogonadotropic hypogonadism in association with insulin gene mutation, and that it is probably caused by metabolic endotoxemia as in other types of diabetes mellitus." (PMID 38793013, 2024). "Indicators of insulin sensitivity, such as muscle fiber type and muscle mass, may help to explain the association between weakness and time to diabetes." (PMID 39119102, 2024). "Diabetes mellitus (DM) is a chronic endocrinological disease that involves chronic states of hyperglycemia caused by abnormalities in metabolism, especially carbohydrates, resulting from the secretion and/or inappropriate action of insulin." (PMID 39791030, 2024). "Diabetes mellitus (DM) encompasses metabolic disorders marked by persistent hyperglycemia and compromised metabolism of carbohydrates, lipids, and proteins due to deficiencies in insulin secretion, action, or both." (PMID 38800470, 2024). "Additionally, a low-protein maternal diet has been associated with reduced fetal β-cell mass and impaired insulin production, raising the risk of glucose intolerance and diabetes in adulthood." (PMID 39770898, 2024). "In diabetes, reduced insulin action in the liver, skeletal muscle, and adipocytes causes metabolic disorders, in which case other nonmetabolic actions in other organs may be expected to be impaired as well." (PMID 39513056, 2024). "Generally, diabetes mellitus is classified into two types: Namely, type one diabetes mellitus (T1D) results from a deficiency of insulin because of B-cell distraction, and type two diabetes mellitus (T2D), which relates to insulin action." (PMID 38468250, 2024). "Moreover, 44.6% (n = 275) knew that insulin is one of the treatments for gestational diabetes, while 45.4% (n = 280) knew that gestational diabetes increases a baby’s risk of obesity and type 2 diabetes mellitus (T2DM) later in life." (PMID 38420077, 2024). "Our findings thus lend support to initiatives that recommend strong preventive measures against central fat accumulation and thereby impaired insulin sensitivity, as central and ectopic fat are thought to be instrumental for increased diabetes risk in South Asian populations." (PMID 39097697, 2024). "Diabetes mellitus (DM) is a chronic metabolic disease characterized by increased blood glucose levels (hyperglycemia), resulting from either the deficiency or action of insulin." (PMID 39125512, 2024). "A recent study has demonstrated that insulin, through the Nrf2 signaling pathway, could increase some antioxidant proteins and prevents neurodegenerative damages associated with diabetes mellitus." (PMID 39004753, 2024). "Previous studies have demonstrated that many factors contribute to the increased risk of fractures in type 2 diabetes mellitus, including impaired insulin signaling, decreased incretin effect, increased oxidative stress, accumulation of advanced glycation end products, and microvascular damage." (PMID 39735781, 2024).
diabetes (continued). "Recent studies have shown that hyperglycemic carbohydrates and insulinotropic milk/dairy products are linked to diabetes and may drive acne pathogenesis, promoting increased insulin and increased body mass index." (PMID 38883100, 2024). "In addition, among patients with T2DM, insulin use and longer duration if diabetes diagnosis of greater than 4 years were associated with worse outcomes." (PMID 38302987, 2024). "Hyperglycemia in diabetes is caused by abnormalities in insulin secretion, which could be managed effectively through proper diet and enzyme inhibition." (PMID 39610875, 2024). "Insulin use may indicate a higher risk of severe DR, emphasizing the need for comprehensive diabetes management and regular ophthalmologic evaluations." (PMID 39867069, 2024). "These alterations in lipid metabolism within the mammary glands might be related to changes caused by diabetes, since insulin is known to be involved in fatty acids synthesis through regulating the desaturation and elongation enzymes." (PMID 39540631, 2024). "Although classical biomarkers such as age, HbA1c and diabetes duration are associated with glycaemic progression, it is unclear how well such variables predict insulin initiation or requirement and whether newly identified markers have added predictive value." (PMID 38374450, 2024). "Hence, recovery from dyslipidaemia is a positive outcome of the current study, which is not only beneficial for regulating insulin sensitivity but also for managing the incident and progression of diabetes-associated heart diseases." (PMID 39279894, 2024). "The dependent variables of the study were the diabetes risk markers (glycemia, insulin, glycosylated hemoglobin and the HOMA-IR index) and the profile of dietary lipids (saturated, monounsaturated, polyunsaturated, trans, cholesterol, EPA + DHA) consumed by the participants during the intervention." (PMID 38318471, 2024). "Notably, it declines rapidly after the onset of insulin-deficient diabetes but can be restored through local and systemic administration of insulin." (PMID 38300646, 2024). "We evaluated key markers of insulin signaling in skeletal muscles in our population, as skeletal muscle contributes to over 85% of glucose disposal in humans of normal weight, and deficits in proximal insulin receptor signaling are associated with diabetes." (PMID 39684905, 2024). "The term “type 3 diabetes” describes the strong association between diabetes and Alzheimer’s disease characterized by impaired insulin signaling, glucose utilization, and metabolism in brain regions essential for higher-order functions such as spatial learning and memory." (PMID 38416718, 2024). "The potential cause for this occurrence may stem from several factors, including a prolonged duration of the pathological process, reduced insulin production, complications associated with diabetes, and a gradual decline in insulin secretion." (PMID 38553464, 2024). "Moreover, nonobese people with insulin resistance have an 80% greater risk of developing diabetes than insulin-sensitive individuals." (PMID 38710948, 2024). "Notably, diabetes treated with insulin had a stronger association with dementia (odds ratio: 3.2, 95% confidence interval: 1.4–7.5)." (PMID 39571101, 2024). "Insulin may exacerbate heart failure by causing water–sodium retention and thereby should be used with caution in older patients with diabetes and concurrent heart failure." (PMID 38571669, 2024). "β-cell loss and reduced insulin in diabetes is predicted to alter gck expression and regulation." (PMID 39580550, 2024). "The association of BrCa with diabetes could be explained through similar pathways such as the activation of the insulin pathway, the activation of insulin- like growth factor pathway, as well as the regulation of sex hormones." (PMID 39061008, 2024). "Akita-like insulin mutations cause rare infantile diabetes described in humans." (PMID 38744890, 2024).
diabetes (continued). "Studies involving the use of insulin and controlling high blood sugar levels in reverting and preventing adverse effects, such as memory loss and cognitive decline in people with diabetes, can lead to finding a new avenue for the treatment of complications of diabetes in the brain." (PMID 39449895, 2024). "Chronic diseases such as diabetes and hypertension are a major cause of morbidity and mortality worldwide, with diabetes mellitus being a disease characterized by chronic hyperglycemia caused by changes in insulin secretion." (PMID 38337933, 2024). "Insights from our work suggest that Lgr4 loss could elevate diabetes risk through mechanisms that involve effects on insulin resistance, glycemic levels, and the production and secretion of insulin." (PMID 39033139, 2024). "In addition, smoking can exacerbate the challenges associated with managing diabetes and regulating insulin levels." (PMID 38792958, 2024). "However, total knockout does not result in neonatal hypoglycaemia but instead dramatically reduces insulin secretion and causes impaired glucose tolerance in adult mice that progresses to overt diabetes when fed a high-fat diet." (PMID 38366195, 2024). "Consistent evidence shows that magnesium deficiency is related to the change in insulin sensitivity and the progress of diabetes, and magnesium metabolic disorder may mediate the impairment of insulin glucose uptake." (PMID 39839287, 2024). "Defective insulin secretion is causal in most forms of diabetes." (PMID 38782979, 2024). "When insulin sensitivity decreases because of damaged insulin signaling, glucose transport to adipocytes is inhibited, causing excessive glucose to remain in the blood, which results in the development of diabetes." (PMID 38732125, 2024). "In the present study, stevia may reduce the rise in blood glucose levels caused by diabetes by increasing insulin secretion in β cells." (PMID 39479688, 2024). "Enhanced insulin sensitivity is associated with improved glucose control and may consequently contribute to a decreased risk of diabetes-related complications." (PMID 38337679, 2024). "Our results highlight the potential of Vox2 in association with insulin in treating diabetes." (PMID 38675446, 2024). "Diabetes is a chronic disorder characterized by hyperglycemia, which results from relative or absolute insulin deficiency, reduced sensitivity of target cells to insulin, and disturbances in glucose, lipid, and protein metabolism." (PMID 39595541, 2024). "Although it is believed that n-3 PUFA may reduce the risk of developing diabetes by modulating insulin sensitivity in phospholipid membranes, the detailed reason for the discrepancy of association of n-3 PUFA and T2D between Asia and non-Asia is unknown." (PMID 37981321, 2024). "Targeting chemerin/chemR23 may be an attractive strategy to improve insulin signalling and vascular function in obesity-associated diabetes." (PMID 39335646, 2024). "However, diabetes is a disease characterized by the destruction of β cells with deficient insulin secretion, chronic hyperglycemia, and vascular complications compromising the peripheral autonomic nervous system." (PMID 39057518, 2024). "The possible explanation is that, in type 2 diabetes mellitus there is body resistance to the insulin, which causes sugar to build up in the blood, leading to damage to the small blood vessels in the body, causing the walls of the blood vessels to become stiff and increasing blood pressure." (PMID 38713690, 2024). "Diabetes is a common chronic disease with many complications, and its main characteristic is high glucose concentration in the blood, which is caused by absolute or relative insulin secretion insufficiency and/or insulin utilization disorder." (PMID 39758348, 2024). "note that Insulin alone or in combination with sulfonylureas could increase the risk of heart failure in people with diabetes." (PMID 39835266, 2024).
diabetes (continued). "KEGG pathways showed that some proteins were enriched in the glycosaminoglycan degradation, glyoxylate and dicarboxylate metabolism, diabetic cardiomyopathy, insulin secretion, and glycolysis/gluconeogenesis pathways, which are all associated with diabetes-related glucose metabolic disorders." (PMID 38609366, 2024). "However, current evidence generally agrees that smoking is a risk factor for diabetes, and in particular that nicotine in tobacco has been found to decrease glucose tolerance, lower insulin secretion, and increase insulin resistance and glucagon secretion." (PMID 39647865, 2024). "Diabetes is a metabolic disorder caused by the body’sinabilityto produce or use insulin." (PMID 39839886, 2024). "Ectopic fat deposition in the pancreas is harmful to pancreatic β-cell function; this may lead, in the long term, to the loss of insulin secretion, hyperglycemia, and frank diabetes." (PMID 39769002, 2024). "In addition, compared with poor care, excellent care in the diabetes group was associated with the lowest mortality rates in the diet-treated and insulin-treated subgroups (diet-treated: HR 0.64, 95% CI 0.61, 0.68; insulin-treated: HR 0.69, CI 0.66, 0.72)." (PMID 39358593, 2024). "Nonetheless, several small studies showed that plasma vasopressin levels are significantly increased in patients with insulin-treated diabetes mellitus and hyperglycemia or in patients with uncontrolled diabetes associated with marked hyperglycemia, plasma hyperosmolality, and polyuria." (PMID 39769071, 2024). "In addition to insulin, other hormones like glucagon, cortisol, and catecholamines can be dysregulated in diabetes, further influencing cardiovascular risk." (PMID 39728296, 2024). "Previous research has noted the importance of measuring postprandial glucose and insulin responses to substrates such as lipids to determine individual variability and how that may impact the risk of developing diabetes and disease." (PMID 38987291, 2024). "Type 2 diabetes mellitus (T2DM) is a disease defined by high blood sugar levels and a relative shortage of insulin, as well as insulin resistance and other chronic metabolic illnesses caused predominantly by diabetes, accounting for more than 90% of diabetic patients." (PMID 38652719, 2024). "Subsequent work showed that the foetal insulin hypothesis also applies to high birthweight, as mutations that promote macrosomia via increased foetal insulin secretion are associated with diabetes in adulthood." (PMID 38380130, 2024). "Diabetic neuropathy has been widely studied at the early stages of the disease, and we further confirmed that db/db mice displayed hyperglycemia and obesity persistent during late-stage diabetes accompanied by substantial loss of insulin-producing β-cells in pancreas." (PMID 38532899, 2024). "Particularly, therapies aimed at preserving pancreatic β-cell function or improving peripheral tissue insulin sensitivity could reduce the risk of diabetes post-COVID-19." (PMID 38627360, 2024). "Next, using insulin as an exemplary therapeutic output, we tested the treatment potential of the grazoprevir-inducible gene switch in an experimental diabetes mouse model of chemically induced insulin deficiency." (PMID 38172533, 2024). "Important peptide hormones associated with obesity and diabetes are glucagon and insulin." (PMID 38250713, 2024). "A study focusing on older adults aged 70–79 found that a dietary pattern including low-fat dairy, fruits, whole grains, poultry, fish, and vegetables may be associated with higher insulin sensitivity, an effective method for preventing diabetes." (PMID 39275148, 2024). "We hypothesized that the observed phenomenon could be attributed to the decline in eGFR, resulting in an elevated risk of diabetes and decreased insulin sensitivity." (PMID 38388456, 2024). "Notably, an imbalance between glucagon and insulin production has been implicated in patients with diabetes mellitus." (PMID 38626157, 2024).